MSTN (myostatin)
Diseases named in the same sentence as MSTN in open-access papers (continued):
Sharing a sentence is not in itself a finding about the gene and the disease.
Obesity (131 papers, 2009 to 2026). Accumulation of substantial excess body fat. "It has been demonstrated that irisin acts as a protective factor and a potential biomarker for obesity-related comorbidities, while alterations in myonectin and myostatin further contribute to cardiometabolic risk in MASLD patients." (PMID 41515940, 2025). "Although MSTN is best known as a negative regulator of muscle mass, animal and cell models suggest that MSTN plays a pathogenic role in insulin resistance in obesity and T2D." (PMID 40171198, 2025). "Previous studies in patients with obesity have shown that hyperinsulinemia caused by obesity enhances the inhibitory effect of myostatin and that this is related to a decrease in SMM." (PMID 40416039, 2025). "Certain gene polymorphisms (eg, in TNF-α, IL-6, or muscle growth regulators such as myostatin) have been implicated in sarcopenia and obesity separately." (PMID 40718355, 2025). "Given that hepatic steatosis is closely associated with obesity and insulin resistance, we next assessed the effects of MSTN deletion on hepatic lipid deposition under HFD conditions." (PMID 38889010, 2024). "Myostatin negatively regulates skeletal muscle growth and appears upregulated in human obesity and associated with insulin resistance." (PMID 37801203, 2024). "Targeting the myostatin pathway potentially offers an approach for treating cancer as well as age-, obesity-, and spinal dystrophy-related muscle loss associated with progressive body wasting and loss of motor function." (PMID 39683624, 2024). "FGF21 and myostatin, myokine factors, are known to be associated with obesity and insulin resistance." (PMID 36981616, 2023). "The elevated levels of myostatin were proved to be associated with obesity and T2DM as it initiates insulin resistance in both human and mouse models." (PMID 37576807, 2023). "As a manifestation of metabolic disorder, obesity has been shown to be associated with increased myostatin expression." (PMID 37288303, 2023). "Several lines of evidence demonstrate that obesity is associated with increased myostatin expression." (PMID 35407437, 2022). "MSTN deficiency reduced liver weight in MSTN knockout piglets, mitigated sepsis-induced liver dysfunction, and protected the liver against obesity-induced insulin resistance." (PMID 35049827, 2022). "Evidence of a positive relationship between myostatin and obesity-associated insulin resistance was provided in murine models." (PMID 35631274, 2022). "In high-fat diet (HFD) mice, mutation-induced reductions in MSTN activity protected against obesity-induced insulin resistance." (PMID 35812316, 2022). "Myokines such as myostatin and irisin are muscle-derived factors possibly involved in obesity-associated diseases." (PMID 35631274, 2022). "From a clinical perspective, circulating MSTN levels are elevated in individuals with obesity, and weight loss reduces MSTN levels and improves insulin sensitivity." (PMID 35740032, 2022). "Meanwhile, MSTN deficiency has an effect on lipids, which can promote brown fat formation in white adipose tissue and fatty acid oxidation to prevent obesity under a high fat diet." (PMID 35049827, 2022). "The overexpression of myostatin in mice causes insulin resistance whereas anti-myostatin antibodies prevent obesity by stimulating fatty acid oxidation and increasing energy expenditure." (PMID 36552772, 2022). "Mice with either mutated or defective myostatin have been shown to be resistant to diet-induced obesity, dyslipidaemia, atherogenesis, and hepatic steatosis." (PMID 34680417, 2021). "Obesity causes ectopic fat accumulation in liver and skeletal muscle, stimulating muscles to produce myostatin and cytokines." (PMID 34440592, 2021). "Recent studies demonstrated an association between the MSTN rs1805086 polymorphism with lower muscle strength, higher obesity risk, and extreme longevity, but the molecular basis of these associations has not been clarified." (PMID 34067816, 2021).
Obesity (continued). "This study aims to evaluate the association between serum adiponectin and myostatin levels and identify independent factors using body composition and metabolic parameters in patients with obesity." (PMID 33465151, 2021). "It has been reported that lower serum myostatin levels are independently associated with metabolic syndrome, obesity, dyslipidemia, and DM." (PMID 34233657, 2021). "Myostatin has been suggested as a diagnostic biomarker to predict obesity-associated comorbidities, due to its increased concentration in skeletal muscle and its significant correlation with IR severity." (PMID 35111794, 2021). "There is high clinical significance in examining the relationship between the body composition of patients with obesity and the secretion dynamics of serum adiponectin and myostatin levels for optimal body weight loss treatments." (PMID 33465151, 2021). "High muscle and serum myostatin concentrations have been documented in both mouse models and humans with obesity and found to be associated with systemic IR." (PMID 34868459, 2021). "This is the first report to confirm the relationship between changes in serum myostatin and adiponectin levels that reflect changes in the body composition of patients with obesity following a weight loss obesity program." (PMID 34233657, 2021). "We aimed to examine the relationships among myostatin, adiponectin, and body composition, depending on the extent of weight loss, in patients with obesity undergoing a weight loss program." (PMID 34233657, 2021). "Increased levels of myostatin promote protein catabolism, inhibit growth of skeletal muscle and associate with obesity and IR." (PMID 35111794, 2021). "Intermuscular lipids are associated with higher levels of myostatin, IL-6, and macrophages infiltration, observed in subjects with obesity." (PMID 34025446, 2021). "Exercise decreases the expression of myostatin in humans and obesity is associated with increased myostatin expression." (PMID 29697773, 2018). "From this data, it can be concluded that elevated levels of myostatin are associated with obesity, and that this contributes to decreased muscle mass." (PMID 27746742, 2016). "The secreted form of MSTN is strongly correlated with human obesity and weight loss, suggesting an emergent and important role for MSTN in the regulation of energy metabolism." (PMID 26580662, 2015). "Further, murine models of loss-of-function MSTN mutations, gene knockout or pro-peptide overexpression are all resistant to high fat diet-induced IR and obesity." (PMID 26580662, 2015). "We therefore re-examined the effect of the high-fat diet on adults and found myostatin null mice were more susceptible to diet-induced obesity through a mechanism involving impairment of inter-organ fat utilization." (PMID 26644908, 2015). "Myostatin, a myokine and negative regulator of skeletal muscle mass, has been implicated in obesity development in other species." (PMID 25390640, 2014). "The myostatin and perilipin pathways play key roles in the regulation of muscle mass and lipolysis respectively and have both been associated with obesity predisposition in other mammalian species." (PMID 24956155, 2014). "Clinical obesity is associated with increased MSTN expression, and MSTN mRNA levels are increased in both adipose and skeletal muscle of obese mice." (PMID 25859286, 2014). "Myostatin gene expression was positively associated with obesity in both mouse and human studies, whilst blocking myostatin function in mature mice elicited positive effects on glucose and insulin dynamics." (PMID 25390640, 2014). "We report that variants of Myostatin gene predispose to obesity, abdominal obesity and low lean body mass in Asian Indians in north India." (PMID 22916099, 2012). "In conclusion, high muscular expression of myostatin is associated to impaired metabolism, systemic inflammation, obesity and poor fitness level in healthy subjects." (PMID 22615949, 2012).
Obesity (continued). "In contrast, deletion or loss of function mutations in myostatin, and conditional muscle-specific overexpression of Akt1, clearly protect against or reverse diet-induced obesity and hepatic lipid deposition." (PMID 20593012, 2010). "The results of this study clearly show an interesting link between susceptibility to high-fat diet induced obesity and myostatin expression." (PMID 20877574, 2010). "MSTN-knockout mice exhibit a remarkable phenotype characterized by increased muscle mass, decreased adipose tissue deposition, and a heightened resistance to obesity induced by high-fat diets or genetic mutations." (PMID 41439973, 2025). "Overall, inhibition of myostatin could be beneficial for obesity and associated metabolic disorders through browning of WAT." (PMID 39764565, 2025). "Thus, myostatin can be associated with insulin resistance (IR), the connection being confirmed by previous research that revealed increased myostatin levels in obesity and enhanced insulin sensitivity and glucose uptake after myostatin expression loss." (PMID 41515940, 2025). "Due to the positive association between MSTN and obesity, insulin resistance indices, and metabolic syndrome, this myokine may also be an important factor in the regulation of energy metabolism." (PMID 41303309, 2025). "In the first instance, experiments investigated whether cross-talk between SAT and skeletal muscle might play a causal role in the obesity-mediated upregulation of myostatin." (PMID 37801203, 2024). "It remains to be investigated whether ectopic fat accumulation, such as intramyocellular lipid content, which is elevated in aged adults with obesity and insulin resistance, play a causative role in the upregulation of skeletal muscle myostatin." (PMID 37801203, 2024). "Skeletal muscle is the target of obesity-induced inflammation, while the obesity-induced inflammation and IR can also cause the release of specific skeletal muscle cytokines, such as IL-6, irisin, myostatin, and muscle growth inhibitor." (PMID 39474255, 2024). "In conclusion, higher serum myostatin levels are independently associated with lower insulin sensitivity in adults with overweight/obesity and may be a marker of or play a mechanistic role in the development of insulin resistance." (PMID 39261976, 2024). "Furthermore, obesity is associated with increased levels of myostatin, a myokine that suppresses muscle growth and promotes osteoclastogenesis, thereby adversely affecting both muscle and bone tissues." (PMID 39902393, 2024). "We sought to determine whether higher serum myostatin levels are independently associated with lower insulin sensitivity in adults with overweight/obesity." (PMID 39261976, 2024). "We hypothesized that higher serum myostatin levels are associated with lower insulin sensitivity in otherwise healthy adults with overweight/obesity." (PMID 39261976, 2024). "Some myostatin gene polymorphisms may be associated with obesity, and higher myostatin levels than controls have been reported in obese patients." (PMID 36769301, 2023). "In view of the important role of myostatin in muscle atrophy, sarcopenia, and fat accumulation, this substance represents a promising direction for future research with respect to aging and obesity being associated with the growing incidence of chronic non-communicable diseases." (PMID 37374197, 2023). "It has been reported that myostatin is involved in the development of OSA and probably also in alcoholics, but in this study, in accordance with the results obtained analyzing the simple variables derived from DEXA, the only OSA criterion associated with myostatin alteration was obesity." (PMID 36769301, 2023). "Besides showing a central role in regulating muscle growth and atrophy, myostatin also regulates metabolic factors and is positively associated with obesity and IR." (PMID 37408184, 2023).
Obesity (continued). "This explorative study aims to investigate whether myostatin and irisin are associated with metabolic parameters, including the vitamin D status in pediatric patients with severe obesity." (PMID 35631274, 2022). "Further research may focus on investigating means to prevent increased myostatin levels in interventional studies, which might open several venues to putative options to treat and prevent obesity-associated diseases." (PMID 35631274, 2022). "One advantage of our study was that our clinical data findings indicated that myostatin and adiponectin showed potential cross-talk, which might affect lean mass in individuals with obesity undergoing a weight loss program." (PMID 34233657, 2021). "However, increased myostatin expression was observed in muscle following a high-fat diet intake in high-fat diet-induced obesity-susceptible mice, whereas myostatin expression levels decreased initially in muscle in high-fat diet-fed resistant mice." (PMID 34233657, 2021). "Furthermore, an aerobic exercise training program combined with modest weight loss in adults with obesity was shown to have significantly reduced myostatin mRNA expression with improved insulin sensitivity." (PMID 34233657, 2021). "Therefore, a prospective longitudinal study is needed for investigating changes in body composition and adiponectin and myostatin levels in patients with obesity during a bodyweight loss program." (PMID 33465151, 2021). "Despite this dramatic anti-obesity phenotype, the underlying molecular basis by which myostatin deletion protects from obesity remains unknown." (PMID 33220490, 2021). "Whether the deleterious association of obesity and myostatin expression reflects an effect of excessive adipose tissue per se, or the product of an obesogenic muscle environment, remains unclear." (PMID 33528828, 2021). "Our data would argue against the beneficial role of myostatin deficiency in the control of obesity." (PMID 26644908, 2015). "However, elevated MSTN expression (circulating and intracellular) is associated with metabolic disorders, such as obesity and type 1 diabetes mellitus (T1DM)." (PMID 26580662, 2015). "Deletion of the transforming growth factor-β family member myostatin, or sequestration of the active peptide by overexpression of the myostatin propeptide/latency-associated peptide (ProMyo) results in both muscle hypertrophy and reduced obesity and IR." (PMID 24473441, 2014). "This study evaluated gene and protein expression of myostatin and its receptor, ActRIIB in adipose tissues and skeletal muscles and serum myostatin concentrations in six lean and six obese animals to explore putative associations between these factors and obesity in horses and ponies." (PMID 25390640, 2014). "As might be predicted, therefore, myostatin null and mutant mice also resist diet-induced obesity and IR, while conversely administration of myostatin to mice causes IR." (PMID 24473441, 2014). "Murine and human studies have clearly implicated myostatin in the development of obesity." (PMID 24956155, 2014). "Furthermore we show that muscle myostatin mRNA content is associated with impaired insulin sensitivity, increased triglycerides, and low-grade chronic inflammation as well as obesity and a poor fitness level." (PMID 22615949, 2012). "Using a comparative approach, we analyzed the effects of high-fat diet intake on myostatin and follistatin expression, spleen cell composition, and potential cytokine expression in high-fat diet induced obesity (HFDIO) resistant (SWR/J) and susceptible (C57BL/6) mice models." (PMID 20877574, 2010). "Together, these results suggest that susceptibility to high-fat diet induced obesity could be influenced by local myostatin activity in a tissue-specific manner and that splenocytes exhibit differential cytokine production in a strain-dependent manner." (PMID 20877574, 2010).
Obesity (continued). "Myostatin-activin pathway inhibitors, initially developed for patients affected by muscle-wasting diseases such as Duchenne muscular dystrophy, show promise for therapeutic applications to preserve muscle mass while reducing fat tissue during weight loss in obesity treatment." (PMID 40104296, 2025). "Thus, factors intrinsic to skeletal muscle may be responsible for the obesity-mediated upregulation of myostatin, and future work to establish causality is required." (PMID 37801203, 2024). "Further research may focus on investigating means to prevent increased myostatin levels in interventional studies, which might open several venues to putative options to treat and prevent obesity-associated diseases in pediatric patients with severe obesity." (PMID 35631274, 2022). "The aim of this study was to investigate if a relationship exists between myostatin, its antagonist follistatin, as well as irisin, with BMI, body-fat mass and various metabolic markers already in children and adolescents, particularly in a high-risk group suffering from severe obesity." (PMID 35631274, 2022). "In addition to IL-6, impaired myostatin and muscle cytokine signaling may contribute to RA-associated sarcopenic obesity." (PMID 30587230, 2018). "Understanding how myostatin responds to metabolic stress and affects biomechanical remodeling offers novel insights into obesity-related muscle and tendon dysfunction." (PMID 41596614, 2026). "This review highlights the multifaceted role of myostatin in obesity, beyond its role in muscle catabolism, to include modulation of structural integrity, metabolism, and mechanical adaptability of the musculotendinous system." (PMID 41596614, 2026). "Previous studies have demonstrated that higher myostatin levels are observed among people with obesity and the inhibition of myostatin decreases fat mass in rodent models, implying its primary effects on fat accumulation." (PMID 40641114, 2025). "Our results resembled previous studies, showing similar benefits of MSTN inhibition in promoting muscle fiber growth and preserving function in various muscle-wasting conditions such as diabetes, cachexia, and obesity." (PMID 40243849, 2025). "In obesity and T2DM mouse models, loss of MSTN mitigates fat accumulation and deviation from healthy glucose metabolism." (PMID 39340593, 2025). "Expression of IRF4 in BAT is strongly correlated with serum MSTN levels, with loss of IRF4 causing obesity, decreased exercise capacity, and increased serum MSTN." (PMID 39340593, 2025). "There is a positive correlation between circulating MSTN levels or its muscle expression and insulin resistance in people with obesity and T2D." (PMID 40171198, 2025). "Mechanistically, MSTN inhibition interacts with insulin sensitivity and obesity through both skeletal muscle-dependent and independent mediation." (PMID 39340593, 2025). "Myotubes from insulin-resistant women with extreme obesity show increased MSTN secretion, suggesting that muscle is a source of increased circulating MSTN levels during obesity and T2D." (PMID 40171198, 2025). "Muscle-biopsy evidence in individuals with obesity shows elevated myostatin and activated SMAD signaling, leading to reduced PGC-1α, defective mitochondrial biogenesis, and intramyofiber lipid accumulation." (PMID 41515940, 2025). "Higher circulating myostatin independently predicts lower insulin sensitivity in adults with overweight or obesity, while reduced irisin levels accompany impaired glucose tolerance and lower aerobic capacity." (PMID 41515940, 2025). "Integrating muscle mass assessment with circulating myokine profiling (myostatin, irisin, IL-15) has been proposed as a strategy to identify metabolically vulnerable obesity phenotypes, supported by emerging multi-center clinical evidence." (PMID 41515940, 2025).